TOP2A (DNA topoisomerase II alpha)
Diseases named in the same sentence as TOP2A in open-access papers (continued):
Sharing a sentence is not in itself a finding about the gene and the disease.
small cell lung carcinoma (9 papers, 1996 to 2025). Small cell lung cancer (SCLC) is a highly aggressive malignant neoplasm, accounting for 10-15% of lung cancer cases, characterized byrapid growth, and early metastasis. "For example, in small cell lung cancer, the expression level of TOP2A is closely related to patient outcomes." (PMID 41284119, 2025). "Abnormal expression of TOP2A is associated with the malignant characteristics of the tumor, for example, the level of expression of TOP2A in small cell lung cancer is closely related to patient prognosis." (PMID 41284119, 2025). "The expression of TOP2A has also been demonstrated in breast, colon, ovarian, and small cell lung cancers as a valuable prognostic marker for tumor advancements and recurrences, and as a predictor of poor survival." (PMID 32368301, 2020). "A panel of doxorubicin-resistant sublines of the human small-cell lung carcinoma cell line GLC4 displays decreasing DNA topoisomerase II alpha (TopoII alpha) mRNA levels with increasing resistance." (PMID 8761362, 1996). "Therefore, it is necessary to analyze the data of small-cell lung cancer obtained from existing databases to ascertain the clinical role of TOP2A in predicting survival outcome and immune response." (PMID 35784467, 2022). "Moreover, TOP2A has also been a valuable prognostic marker for tumor advancements, recurrences, and predictors of poor survival in a variety of cancers, such as breast, ovarian, colon, and small cell lung cancer." (PMID 33868991, 2021).
triple-negative breast carcinoma (9 papers, 2013 to 2025). An invasive breast carcinoma which is negative for expression of estrogen receptor (ER), progesterone receptor (PR), and human epidermal growth factor receptor 2 (HER2). "TOP2A encodes topoisomerase (DNA) II alpha, somatic mutations in a TOP2A immunohistochemical score may be important in predicting response to immunotherapy treatment for triple-negative breast cancer." (PMID 36567949, 2022). "The expression of TOP2A in triple-negative breast cancer was quantitatively detected and analyzed using quantum dot-based immunofluorescent imaging." (PMID 38730959, 2024). "This approach, compared with conventional immunohistochemistry, validated the enhanced accuracy and prognostic significance of TOP2A expression, establishing it as an independent prognostic indicator in triple-negative breast cancer." (PMID 38730959, 2024). "A protocol for the prognostic diagnosis of triple-negative breast cancer was proposed based on the visualisation of the topoisomerase 2 alpha (TOP2A) marker using QDs." (PMID 37511027, 2023). "Higher expression of BiP protein significantly correlated with triple-negative breast cancer and the TOP2A proteogenomic status, with poor differentiation (basal)." (PMID 36547124, 2022). "On the other hand, the BiP-H group was significantly correlated with triple-negative breast cancer, TOP2A proteogenomic status, and the xCell immune score." (PMID 36547124, 2022). "Markers for cell proliferation like Top2a, Birc5, and Mki67 are highly expressed, so are markers for metastasis like Msln, Ect2, and Plk1, which are known to be overexpressed in triple-negative breast cancer (TNBC)." (PMID 32793490, 2020). "Among 126 triple-negative breast cancer (TNBC) tumors, no amplifications of TOP2A were found." (PMID 23537287, 2013).
COVID-19 (8 papers, 2022 to 2024). A disease caused by infection with severe acute respiratory syndrome coronavirus 2. "Among the analyzed core genes, only SPAG5 and TOP2A were characterized by a statistically significant up-regulation in critical COVID-19 stage compared to mild COVID-19 stage, which is in good agreement with published data." (PMID 39596028, 2024). "In the COVID-19 dataset, TYMS(AUC:0.952), RRM2(AUC:0.954), CDCA2(AUC:0.946) and TOP2A(AUC:0.958) exhibited good diagnostic efficiency for differentiating the patients with SARS-CoV-2 from healthy controls." (PMID 35958619, 2022). "In consistence with the result of our study, TOP2A has been identified as a hub gene that could govern many cellular processes by protein–protein interactions in COVID-19 patients." (PMID 35721149, 2022). "COVID-19 neutrophils preferentially transitioned from the apex of the trajectory, which was an immature state (TOP2A-expressing) to an IFNactive state characterized by IFITM1, IFITM2 and IFI6 expression (clusters 1–4 and 5; Online Atlas) and activation of type I IFN signaling pathways." (PMID 34782790, 2022). "For the remaining five hub genes (TYMS, CDCA2, TOP2A, RRM2 and IFI44), there are no studies reporting their role in COVID-19 or pSS, which emphasizes its importance in future research." (PMID 35958619, 2022).
neuroblastoma (8 papers, 2006 to 2026). Neuroblastoma (NB) is the most common solid, extracranial childhood tumor. "Many of these, e.g. NME1, PYCR1, TK1, BIRC5 and TOP2A, are located on Chr 17q, are upregulated in unfavorable neuroblastoma and associated with poor patient outcome." (PMID 37246217, 2023). "Next to IGF2BP1, this analysis unraveled top-ranking of BIRC5 and TOP2A among common essential as well as NME1 among neuroblastoma essential Chr 17q genes." (PMID 37246217, 2023). "Remarkably, we found that CX-5461 was between 2- and 4-fold more effective at inhibiting TOP2B, compared to TOP2A (P = 2.8 × 10−4), confirming the broader relevance of this mechanism outside neuroblastoma cells." (PMID 34753908, 2021). "We evaluated the effect of palbociclib on the Rb/E2F pathway in neuroblastoma cells by measuring the mRNA expression levels of direct E2F target genes, topoisomerase 2A (TOP2A), cyclin E2 (CCNE2), and thymidine kinase (TK1)." (PMID 26225123, 2015). "This revealed CX-5461 treatment-induced TOP2cc formation, for both TOP2A and TOP2B, in all four neuroblastoma cell lines tested, again consistent with CX-5461 trapping TOP2 to DNA and behaving as a classical topoisomerase II poison." (PMID 34753908, 2021). "We first observed that although TOP2A and TOP2B were both overexpressed in neuroblastoma cell lines, the magnitude of TOP2B overexpression was substantially larger." (PMID 34753908, 2021).
viral infection (8 papers, 2019 to 2025). "To determine whether Top2α inhibitor-treated T cells mirror the telomere loss seen in patients with viral infections, we measured the telomere length in ICRF-treated T cells by Flow-FISH." (PMID 32193368, 2020). "Here, we investigated the role of topoisomerase IIA (Top2α, an enzyme that is essential in resolving entangled DNA strands during replication) in telomeric DNA damage and T cell dysfunction during viral infection." (PMID 32193368, 2020). "While the mechanisms leading to Top2α inhibition during chronic viral infections remain unclear, multiple factors may play a role." (PMID 32193368, 2020). "Moreover, reduning injection might also control the virus infection by directly targeting viral proteins, such as DNA topoisomerase 2-alpha (TOP2A) to inhibit the virus replication." (PMID 31379563, 2019). "Several epigenes previously involved in response to viral infections stood out in our protein interaction analysis, such as BRD4, TOP2A, and TRIM28." (PMID 34031419, 2021). "Nevertheless, these novel findings demonstrate, for the first time, the role of Top2α in DDR and shed light on the molecular aspects of immunomodulation during human viral infections." (PMID 32193368, 2020). "The mRNA levels of Top2α in CD4 T cells isolated from virus-infected patients remained unchanged compared to HS, indicating that Top2α inhibition occurs primarily at the post-transcriptional level during viral infection." (PMID 32193368, 2020).
lymph node metastasis (7 papers, 2019 to 2025). "Interestingly, TCGA data revealed that TOP2A expression statistical significantly associates with lymph node metastasis (N stage), that TOP2A was higher expressed in N3 comparing to N0 and N2 adenocarcinoma, and in N1, N3 comparing to N0, N2 squamous cell carcinoma." (PMID 31528121, 2019). "The expression TOP2α intensity was higher in the premenopausal group (mean rank: 54.28 > 42.90, p = 0.040) and lymph node metastasis group (mean rank: 55.19 > 43.64, p = 0.037)." (PMID 35204496, 2022). "The overexpression of TOP2A in NSCLC tissues is related to lymph node metastasis, which can promote cell proliferation and invasion." (PMID 31726467, 2019). "TOP2A is highly expressed in HGSOC tissues and cisplatin-resistant cells, with high levels strongly associated with tumor progression (advanced stage, high grade, lymph node metastasis) and poor prognosis." (PMID 41235254, 2025). "Univariate Cox analysis identified TNM stage (p = 0.003), T (p = 0.040), lymph node metastasis (p = 0.012), VALSG stage (p < 0.001), and TOP2A expression (p = 0.001) as variables that were significantly related to overall survival." (PMID 40765849, 2025). "The evaluation included variables such as age, gender, tumor location, TNM stage, T stage, lymph node metastasis, VALSG stage, and expression levels of TOP2A and CDK1." (PMID 40765849, 2025). "Therefore, TOP2A, HLA-ABC, lymph node metastasis, and distance can be regarded as independent prognostic factors of SCLC." (PMID 35784467, 2022).
meningioma (7 papers, 2013 to 2024). A generally slow growing tumor attached to the dura mater. "Our meta-analysis revealed the association of the high expression of cyclin A and TOP2A with the high-risk of recurrence of meningioma patients." (PMID 38758750, 2024). "Abnormal expression of cyclin A and TOP2A may linked to the irregular cell proliferation of meningioma patients." (PMID 38758750, 2024). "The potential of TOP2A expression as a biomarker to predict prognosis of 669 meningioma patients in 3 studies was analyzed." (PMID 38758750, 2024). "An array meta-analysis revealed approximately 10-fold higher expression of TOP2A in GIII compared with GI meningiomas." (PMID 31083655, 2019). "DNA topoisomerase 2-alpha (TOP2A) was significantly upregulated in GII + GIII meningiomas in four studies compared with GI." (PMID 31083655, 2019). "DNA topoisomerase 2-alpha (TOP2A) was markedly upregulated in GII + GIII meningiomas in four studies." (PMID 31083655, 2019). "Of note, overexpression of transcripts for TOP2A and DLG7 has been recently identified in grade III meningioma in comparison to grade I meningioma." (PMID 24349376, 2013). "2D meningioma cells were subdivided into five clusters including proliferating cells expressing the FOXM1 target genes CCNB1 and TOP2A, cells enriched for metabolic pathways, and cells enriched for extracellular matrix organization and integrin interaction pathways." (PMID 32968068, 2020).
nasopharyngeal carcinoma (7 papers, 2015 to 2026). A carcinoma arising from the nasopharyngeal epithelium. "Module analysis of the PPI network revealed the top ten hub genes identified expect TOP2A were belonged to module 1, indicating that these hub genes had close interaction and together determined the key pathway associated with nasopharyngeal carcinoma." (PMID 28969025, 2017). "Moreover, the top ten hub genes expect TOP2A were belonged to module 1, which together determined the key pathways associated with nasopharyngeal carcinoma." (PMID 28969025, 2017).
pancreatic adenocarcinoma (7 papers, 2019 to 2025). "Survival analysis results of this study showed that TOP2A was associated with poor survival in pancreatic adenocarcinoma and the survival probability was obvious between the high expression of TOP2A and the medium/low expression group." (PMID 31412643, 2019). "The survival analysis results showed that MELK and TOP2A were linked with poor survival in pancreatic adenocarcinoma (p < 0.01)." (PMID 31412643, 2019). "DNA topoisomerase II alpha, syndecan 1, maternal embryonic leucine zipper kinase and proto-oncogene receptor tyrosine kinase Met were significantly linked with poor survival in pancreatic adenocarcinoma." (PMID 31412643, 2019). "In research of forecasting gemcitabine sensitivity with pancreatic adenocarcinomas patient objects, a different expression of TOP2A was discovered in gemcitabine sensitive tumors which authenticated as one of potential genes linked with resistance to drug." (PMID 31412643, 2019).
soft tissue sarcoma (7 papers, 2012 to 2023). A malignant neoplasm arising from muscle tissue, adipose tissue, blood vessels, fibrous tissue, or other supportive tissues excluding the bones. "TOP2A overexpression was also correlated with a better pathohistological response and a decreased risk of relapse in locally advanced soft tissue sarcomas." (PMID 34638362, 2021). "The predictive properties of TOP2A have been described in several studies, with varying results: The overexpression of TOP2A was linked to a poor prognosis and unfavorable five-year overall survival (OS) in different soft tissue sarcomas." (PMID 34638362, 2021). "TOP2A and SIRT1 showed distinct expression patterns in different high-risk soft tissue sarcoma subtypes." (PMID 34638362, 2021). "In the present study, we analyze the expression of TOP2A and SIRT1 in a large and well-characterized cohort of high-risk soft tissue sarcoma patients with a long-term follow-up and correlate our findings with clinical tumor characteristics and survival data." (PMID 34638362, 2021). "In this study, we analyzed the expression of TOP2A and SIRT1 in a well-characterized cohort of high-grade soft tissue sarcoma patients using tissue microarrays and immunohistochemistry." (PMID 34638362, 2021). "Strengths of this study were the analysis of TOP2A and SIRT1 on a large patient cohort of high-grade soft tissue sarcomas." (PMID 34638362, 2021). "In another study of our group, TOP2A amplification did not correlate with FISH results in soft tissue sarcomas." (PMID 23398928, 2013).
astrocytoma (6 papers, 2013 to 2024). "EGFR aberrations including gene amplification and EGFRvIII mutation, PTEN mutation, as well as TOP2A, RRM1 and TS overexpression were significantly more prevalent in GBM than grade III astrocytomas." (PMID 26933808, 2016). "Compared with lower-grade astrocytomas and normal brain tissue, TOP2A transcription levels in GBM patients increased significantly, which is a useful prognostic indicator and may guide temozolomide chemotherapy." (PMID 36238156, 2022).
endometrial cancer (5 papers, 2017 to 2023). Primary or metastatic malignant neoplasm involving the endometrium (mucous membrane that lines the endometrial cavity). "Aberrant expression levels of four genes out of 12 core DEGs showed a significant (P < 0.05)association with poor prognosis of endometrial cancer, and this included two up-regulated (TOP2A and ASPM) and two down-regulated (FOXL2 and EFEMP1) genes." (PMID 32555395, 2020). "Another gene of interest on this list is Top2a, a gene highly expressed in stem cell populations and known to play a role in endometrial cancer." (PMID 36328762, 2023). "TOP2A was also reported to be a predictive biomarker in endometrial cancer patients receiving taxane-containing adjuvant chemotherapy." (PMID 34116668, 2021). "Further validation in endometrial cancer cells showed that indeed TOP2A, ASPM, FOXL2 and EFEMP1 were significantly regulated." (PMID 32555395, 2020). "A comparison with normal cells showed that TOP2A was highly expressed in endometrial cancer cells, which was consistent with the resultsfrom bioinformatics analysis above." (PMID 32555395, 2020). "Previous studies have reported that aberrant expression of TOP2A is related to the stage of endometrial cancer and its progression." (PMID 32555395, 2020). "Furthermore, a cross comparison of common DEGs across the three datasets revealed that TOP2A, ASPM, FOXL2 and EFEMP1 were potential biomarkers for distinguishing endometrial cancer, and this was significantly associated with the survival ratios among patients." (PMID 32555395, 2020). "We found up-regulation of TOP2A and ASPM in endometrial cancer tissues or cells, while EFEMP1 and FOXL2 were down-regulated." (PMID 32555395, 2020). "Analysis of qRT-PCR assay revealed that expression of mRNA for TOP2A and ASPM are up-regulated in endometrial cancer cells, whereas those of EFEMP1 and FOXL2 are down-regulated." (PMID 32555395, 2020). "Particularly, expression of TFAP2A, MMP12, TOP2A, ASPM and CFB were higher in endometrial cancer relative to normal tissues." (PMID 32555395, 2020). "In summary, four core genes (TOP2A, ASPM, EFEMP1 and FOXL2) and several interesting pathways involved in endometrial cancer were identified." (PMID 32555395, 2020). "Finally, we performed a survival analysis and identified four genes (TOP2A, ASPM, EFEMP1, and FOXL2) that play key roles in endometrial cancer." (PMID 32555395, 2020).
kidney cancer (5 papers, 2020 to 2025). Primary or metastatic malignant neoplasm involving the kidney. "Furthermore, GENT2 utilized to assess gene expression in liver and kidney cancer tissues where TOP2A showed significant upregulation in both cancers, with high statistical significance and fold change values." (PMID 40390492, 2025).
medulloblastoma (5 papers, 2018 to 2024). A malignant, invasive embryonal neoplasm arising from the cerebellum. "Studies have also revealed that TOP2A is upregulated in medulloblastoma and negatively correlates with the survival time of patients with MB." (PMID 39846632, 2024). "We found frequent TOP2A expression, which has been previously noted in medulloblastoma." (PMID 29869738, 2018). "We then analyzed the expression of TOP2A in GSE85217, which consisted of 763 primary medulloblastoma samples." (PMID 35912241, 2022). "High expression of MRP1 (89%, 8/9 tumors), TUBB3 (86%, 18/21 tumors), PTEN (85%, 28/33 tumors), TOP2A (84%, 26/31 tumors), thymidylate synthase (TS; 80%, 24/30 tumors), RRM1 (71%, 15/21 tumors), and TOP1 (63%, 19/30 tumors) were found in medulloblastoma." (PMID 29869738, 2018).
renal cell carcinoma (5 papers, 2019 to 2023). "TOP2A is reported to be a novel prognostic marker in renal cell carcinoma." (PMID 31788359, 2019).
squamous cell carcinoma (5 papers, 2018 to 2023). A carcinoma arising from squamous epithelial cells. "Statistical analysis results showed that TOP2A positive staining ratio was higher in squamous cell carcinoma than in adenocarcinoma (P = 0.000)." (PMID 31528121, 2019). "TOP2A overexpression was observed in 60.2% of squamous cell carcinoma and 83.3% of adenocarcinoma." (PMID 34705880, 2021). "In addition, a 40% difference in the expression of p16 (high) versus TOP2A (high) biomarkers (100% versus 60%) observed in the squamous cell carcinoma may imply that the p16 biomarker is more specific for squamous cell carcinoma than the TOP2A biomarker." (PMID 34705880, 2021). "Additionally, Oncomine analysis of cancer vs normal samples revealed that TOP2A expressed statistical significantly higher in all subtypes of NSCLC, including adenocarcinoma, squamous cell carcinoma and large cell carcinoma comparing to normal tissues." (PMID 31528121, 2019). "Both Oncomine and GEPIA analysis suggested the aberrant gain of expression of TOP2A in NSCLC, including adenocarcinoma (483 cancer and 347 normal cases analyzed) and squamous cell carcinoma (486 cancer and 338 normal cases analyzed) comparing to normal lung tissues." (PMID 31528121, 2019).